CD4 (CD4 molecule)
Diseases named in the same sentence as CD4 in open-access papers (continued):
Sharing a sentence is not in itself a finding about the gene and the disease.
COVID-19 (continued). "This was significant for the saRNA previous COVID-19 group when compared to either non-saRNA groups (CD8+:CD4+ ratio GM 0.3 (sd±5.1) and 0.1 (sd±11.8) in COVID-19 naïve and previously infected respectively)." (PMID 36194628, 2022). "Across CD4+, CD8+, and NK cells, we found cell cycle and redox state pathways were enriched for differentially expressed genes in more severe hospitalized COVID-19 cases; interferon pathways in less severe disease; and TNF signaling in community cases versus healthy volunteers." (PMID 35216673, 2022). "Indeed, many T cell subsets proliferate during COVID-19, including those usually quiescent, such as TCM and TEM subsets, with 10-fold increases in blood CD4 and CD8 TEM cells in G1 or S-G2/M cell cycle phases." (PMID 35407485, 2022). "We observed that FoxP3- but not FoxP3+ CD4+ T cells from children with COVID-19 showed an increased expression of CD39 (p<0.05 and p<0.01 for non-severe and severe vs controls, respectively)." (PMID 35663467, 2022). "Recent studies suggest that SARS-CoV-2 infection in HIV infected patients, those are not treated with ART or has low CD4 count, have increased severity of COVID-19 compared to those who are negative for HIV." (PMID 35281029, 2022). "Although not significant, we also observed a trend towards a higher CD4+ T-cell proliferative response in vaccinated subjects than in mild-COVID-19 patients." (PMID 35744768, 2022). "Analysis of COVID-19 severity in the vaccinated subgroup shows that fractions of cases with no lung tissue damage (CT 0) in HIV+ patients with CD4+ T-cell counts ≥ 350 cells/μl was significantly higher than in the matching unvaccinated subgroup (p = 0·043)." (PMID 35340627, 2022). "Compared with mild and survivor COVID-19 cases, severe and non-survivor cases had lower counts of CD4/CD8 T-cells and higher levels of IL-10." (PMID 35572964, 2022). "This is supported by studies screening SARS-CoV-2 epitopes in COVID-19 and uninfected patients which have observed SARS-CoV-2 epitopes specific CD4+ and CD8+ T cell responses in SARS-CoV-2 uninfected individuals, which share homology with epitopes in other human coronaviruses." (PMID 35014605, 2022). "In addition, the frequencies of IFN-γ–producing CD3+CD4+ and CD8+ T cells were dramatically increased in patients with extremely severe COVID-19." (PMID 36250073, 2022). "We also identified elevated CCR4 levels on transitional memory CD4+ and CD8+ T cells in these individuals highlighting that enhanced homing of T cells to the lung might exacerbate COVID-19." (PMID 36433939, 2022). "More importantly, unlike the limited DTU and DTE changes shown in mild COVID-19 patients, significant changes were observed in severe COVID-19 patients across all cell types among PBMCs, including B cell, DC, CD4+ T cell, CD8+ T cell, monocyte and NK cell." (PMID 35421082, 2022). "Since T lymphocytes population decreased in COVID-19 patients and CD4 + T lymphocytes showed a high viral antigen-positive rate, we then investigated whether SARS-CoV-2 infects CD4 + T lymphocytes." (PMID 35277473, 2022). "Besides, we identified a CD40-CD40 ligand interaction-mediated increased inflammatory, immune and stress response by the monocyte, NK cells, CD4+ TCM, and CD8+ T cell populations in the COVID-19 patients." (PMID 36532041, 2022). "In general, the number of CD4+ and CD8+ T cells in lymph nodes decrease in severe COVID-19; therefore, these cells may also decrease in the peripheral blood." (PMID 35252273, 2022). "In the lungs of fatal COVID-19 cases with ALI, we identify prominent infiltration of CD4+ macrophages expressing high levels of T cell activation and costimulation genes, which strongly correlates with increased extent of alveolar epithelial cell depletion and CD8+ T cell cytotoxicity." (PMID 35446789, 2022).
COVID-19 (continued). "The recent availability of radiopharmaceuticalS that specifically target CD4 + or CD25 + cells could provide more information on the trafficking and distribution of these cell subsets in COVID-19 patients." (PMID 35486145, 2022). "Moreover, current COVID-19 vaccines are known to induce a strong poly-specific T-cell response mediated by IFN+ or IL-2+ CD8+ and CD4+ Th1-cells." (PMID 35990701, 2022). "In agreement with antibody data, the frequencies of spike-specific B cells and CD4+ T cells significantly increased in naive individuals but not in individuals who have recovered from COVID-19 after the booster administration." (PMID 35139036, 2022). "Nevertheless, future in vitro studies should examine whether memory CD4 T cells in PBMC, in particular cTfh, from recovered COVID-19 patients, can boost anti-spike antibodies by memory B cells in vitro, analogous to previous studies for other recall antigens." (PMID 36544780, 2022). "The strong increase in ISGs in non-pneumonic compared to pneumonic COVID-19 patients was reflected by an elevated ISG-score across CD4+ T cells, NK cells and was particularly prominent in monocytes." (PMID 35197461, 2022). "Memory CD4+ and CD8+ T cells specific for SpiN could be detected in the blood of both individuals vaccinated with Coronavac SARS-CoV-2 vaccine and COVID-19 convalescent donors." (PMID 35977933, 2022). "Thus CD4 + and CD8 + T cells in severe COVID-19 patients presented with concomitant over-expressions of co-inhibitory molecules PD-1, PD-L1, CTLA-4 and TIM-3 in accordance with the development of a state of T exhaustion after severe SARS-Co-V2 infection." (PMID 35246776, 2022). "The molecular mechanisms of Foxp3 expression and the antigen-specific response of CD4+ and CD8+ Treg cells in COVID-19 remain unclear." (PMID 36326397, 2022). "Our meta-analysis shows that COVID-19 alters the status of human host immunity by driving the depression of adaptive immunity, manifesting in the lower counts of CD4 and CD8 T-cells more evident in severe and non-survivor cases." (PMID 35572964, 2022). "As per univariate and multivariate prognostic analyses, a few important genes, including ALPL, ANGPT2, CD4, G6PD, SERPINE1 and TNNI3, may serve as independent prognostic factors for HCC patients with COVID-19." (PMID 36275701, 2022). "Increased production of TNFα by CD4+ T cells and CD8+ T cells in response to COVID-19 plasma exosomes may contribute to differentiation of Th17 T cells." (PMID 36526691, 2022). "As seen with antiviral CD4+ T cells, CD8+ T cell responses (CD8+CD69+41BB+) against SARS-CoV-2 spike–containing CD8-A MP and CD8-B MP were detectable in the majority of children with convalescent COVID-19 (74% and 75% with FC > 2, respectively)." (PMID 35044955, 2022). "On the contrary, the lack of SARS-CoV-2-specific CD4+ and CD8+ T cells was associated with COVID-19 severe disease." (PMID 35891267, 2022). "We also find elevated levels of KIR+CD8+ T cells, but not CD4+ regulatory T cells, in COVID-19 patients, correlating with disease severity and vasculitis." (PMID 35258337, 2022). "In the lungs of COVID-19 patients, IL-6 can be released by SARS-CoV-2 infected respiratory epithelial cells, as well as by infiltrating CD14+CD16+ monocytes-macrophages and CD4+ T cells." (PMID 35340805, 2022). "Our results also showed that CD4+T cell counts were not statistically significant for acceptance of COVID-19 vaccination by stratified and multivariate analysis." (PMID 35578187, 2022). "However, there is an increase in the frequency of CD4+CD39+ and CD8+CD39+ T cells with greater expression of CD39 in patients with severe COVID-19, indicating the prevalence of activated T cells or even regulatory T cells in infected subjects." (PMID 36248842, 2022). "Finally, we found IFNAR1 and IFNAR2, a receptor for type I interferon (IFNα) to be upregulated in the CD4+ TCM and classical monocytes of the COVID-19 patients, compared to the others." (PMID 36532041, 2022).
COVID-19 (continued). "Notably in both populations, STAT3 phosphorylation predominated, with a >7-fold increase in phospho-STAT3 in CD4 T cells and a >3-fold increase in CD8 T cells in severe COVID-19 subjects vs. healthy donors." (PMID 35421120, 2022). "It seems that CD4+ T-cells in severe COVID-19 patients were in an activated status but not chronically, whereas they showed upregulation of PD1 expression." (PMID 36359755, 2022). "The same trend was observed when hospitalized patients were compared to non-hospitalized COVID-19 patients: 7.1% (4.7–10.5) vs. 5% (2.9–8) (p = 0.001 for CD4+) and 20.4% (11.9–27.6) vs. 14.1% (7.9–22.6), (p = 0.012 for CD8+)." (PMID 35203509, 2022). "Immunofluorescence microscopy was conducted to reveal the localisation of TREM-2 in CD4+ T cells in lung tissue of non-severe COVID-19 patients." (PMID 36211412, 2022). "In this report, we demonstrate that COVID-19 plasma exosomes stimulate protein expression of TLR3 as well as TLR7 and TLR9 in CD4+ T cells, CD8+ T cells, and CD14+ monocytes compared with cells that remained untreated, treated with plasma exosomes from non-COVID-19 or healthy donors, or poly(I:C)." (PMID 36526691, 2022). "B lymphocytes and CD4+ and CD8+ T lymphocytes were reported to be reduced in severely ill and critically ill COVID-19 patients, which could be related to patient outcomes." (PMID 35493744, 2022). "In COVID-19, a new zoonotic disease which has resulted in pandemic, relevant efforts carried out in recent months have identified hundreds of epitope peptides recognized by CD8+ cytotoxic, and CD4+ helper T cells." (PMID 35328398, 2022). "Within the CD4+ T cell compartment, children with MIS-C exhibited decreased absolute numbers of transitional memory cells, stem cell memory and regulatory CD4+ T cells when compared with acute COVID-19 children." (PMID 36322537, 2022). "Importantly, donors with previous COVID-19 showed a significant increase in effector memory (CD62Lneg CD45RAneg) and effector (CD62Lneg CD45RA+) S-specific CD4 T-cells following vaccination." (PMID 36139625, 2022). "Our T cell receptor repertoire analysis shows a higher expansion/dominance and a lower richness of CD8+ but not CD4+ T cell clones in progressive COVID-19 in progressive patients relative to stable patients." (PMID 35064122, 2022). "Furthermore, CD4+ T cells also express interferon-gamma (IFN-gamma), a cytokine able to inhibit viral replication; however, seriously ill COVID-19 patients show reduced IFN-gamma-producing CD4+ T cells compared to convalescent individuals." (PMID 35860236, 2022). "We observed a trend toward an increase in the percentage of IL-6+ monocytes and a decrease in the percentage of CD4+IFN-γ+ and CD8+IFN-γ+ lymphocytes in COVID-19 patients, indicating that mononuclear cells support a high concentration of IL-6 and a low response to IFN-γ." (PMID 35901034, 2022). "A previous study reported differences in the peripheral blood counts of CD3+, CD4+, and CD8+ T cells in patients with COVID-19, all of which decreased with increasing disease severity, and also that lymphocyte subset levels were helpful in assessing the disease and determining the prognosis." (PMID 36582384, 2022). "The importance of SARS-CoV-2-specific T cells is further supported by the infection resolution in a COVID-19 patient who did not produce neutralizing antibodies but had instead antigen-specific CD4 and CD8 T cells." (PMID 35757770, 2022). "In particular, COVID-19 moderate patients and recovered individuals from severe disease, when compared to HD, reported higher percentages of IFN-γ+IL-2+TNF+, IFN-γ+TNF+ and IL-2+TNF+ within CD4+ T cells." (PMID 35887351, 2022). "Having any comorbidity, CD4 count of < 200 cells/mm3, not being on ART, and active opportunistic infection were independent risk factors for developing severe COVID-19." (PMID 36192742, 2022).
COVID-19 (continued). "Furthermore, the expression level of HLA-DR and CD38 on CD4+ and CD8+ T cells in peripheral blood significantly increased in patients with COVID-19, and the maximum values were found in patients with a poor disease outcome." (PMID 35632823, 2022). "Unlike CD8 T cells, the ratio of CD4 to CD8 (CD4/CD8), CD4 + T cells, and total T-cell numbers in COVID-19 critical patients were significantly decreased (p < 0.001) compared to mild cases." (PMID 36403042, 2022). "According to recent research, SARS-CoV-2 infection may largely disrupt T lymphocytes, specifically CD4+ and CD8+ T cells, which may be heavily involved in the pathological process of COVID-19." (PMID 35444867, 2022). "In our study, we found a mobilization of memory CD4 T-cells responding to SARS-CoV-2 M peptides following vaccination in some donors without previous COVID-19." (PMID 36139625, 2022). "A thorough examination of CD4+ and CD8+ T cells and B cells specific for various SARS-CoV-2 proteins indicated that coordinated activation of a humoral and cellular branch of the adaptive immune system mostly correlates with the milder COVID-19 form." (PMID 35603211, 2022). "Additionally, T-cell responses, including CD4+ and CD8+ T cells, also play a crucial role in controlling COVID-19 by decreasing viral replication (53, –, 56)." (PMID 35968964, 2022). "M-specific CD4 T-cells were most abundant in vaccinated donors with previous COVID-19 without differences between healthy and cancer patients." (PMID 36139625, 2022). "Taken as a whole, milder cases of COVID-19 in the non-hospitalized group resulted in stronger correlations between SARS-CoV-2-specific CD4+ T cell responses and antibody responses, suggesting more coordinated cellular and humoral immunity." (PMID 35857584, 2022). "Our study showed that SARS-CoV-2-specific CD4+ and CD8+ T cells in convalescent COVID-19 patients could persist up to 13 months." (PMID 35102140, 2022). "In contrast, the absolute counts of total T lymphocytes, CD4+, CD8+ T subpopulations and NK cells were all reduced potently in the vast majority of severe COVID-19 patients, even below the lower limit of normal, and these reductions are closely-associated with the severity of COVID-19 cases." (PMID 35903092, 2022). "Importantly, we observed a lower pseudotime in the COVID-19 patients (except for the CD8+ TEM and CD4+ TCM), possibly indicating a faster transition from one cell type and/state to another." (PMID 36532041, 2022). "Indeed, one significant mechanism with which TNF-α mediates lung inflammation and ARDS, appears to be the reduced CD4+ and CD8+ T-cell counts in patients with severe COVID-19." (PMID 36289890, 2022). "Also, it was stated that CD4+ T cells appeared at a higher frequency and with more numerous corresponding epitope presentations than CD8+ T cells in the recovered COVID-19 patients." (PMID 35603211, 2022). "In the early stages of COVID-19, a low proportion of naïve CCR7 CD4+T cells may be an independent early predictor of patient death." (PMID 36420258, 2022). "Braun and colleagues reported that around 35% of seronegative SARS-CoV-2-unexposed healthy donors had CD4+ T cells that were reactive mainly against the C-terminal portion of the SARS-CoV-2-S protein, although this was a lower proportion than in COVID-19 patients." (PMID 36275696, 2022). "In contrast, robust CD4+ and CD8+ responses—the majority of which are directed against the S protein—are detected in convalescent COVID-19 patients and are much more variable in acute severe COVID-19." (PMID 35746512, 2022). "Frequencies of CD25hiFoxP3+ in CD4+ T cells were significantly decreased in the moderate and severe COVID-19 non-HD population, but not in the COVID-19 HD population." (PMID 35265078, 2022). "Lastly, SARS-CoV-2-responding CD4 T-cells were qualitatively different between convalescent COVID-19 participants and participants who did not experience COVID-19-associated symptoms." (PMID 34140294, 2022).
COVID-19 (continued). "Besides, information regarding the correspondence between levels of T cell responses (CD4+ and CD8+) during different COVID-19 stages is scarce—hence the importance of this study." (PMID 35196808, 2022). "Although IFN-γ levels of CD4+ T cells of COVID-19 patients did not have a significant difference with that of healthy controls, they were observed to be decreased from mild to severe patients." (PMID 36110850, 2022). "Conversely, subjects with decreased IL-2 and IFN-gamma expression and increased PD-1 production in CD4+ and CD8+ T cells in response to polyclonal stimuli tended to display the most severe form of COVID-19, including respiratory distress and mechanical ventilatory support needing." (PMID 35860236, 2022). "T lymphocyte recruitment to infected lung tissues and T lymphocyte apoptosis/necrosis caused by the cytokine storm might be crucial determinants of CD4+ and CD8+ T-cell lymphopenia in severe COVID-19 cases." (PMID 35833134, 2022). "The UK Department of Health and US Centers for Disease Control and Prevention released guidance that recommended PLWHA, regardless of CD4 count, should be vaccinated against COVID-19." (PMID 35486810, 2022). "In contrast, CD4 CTL T-cells and NK-cell subsets displayed increased expression of effector activation markers (GZMB, GZMH, CCL4, XCL2) and ISGs in patients who succumbed to COVID-19." (PMID 35169146, 2022). "Next, in these three groups: COVID-19(+), HC, and COVID-19(−) virus group we analyzed median proportion and GMF intensity of: CD25, CD45RO, CD38, and HLA-DR markers on CD4 and CD8 lymphocytes T. We compared the differences in expression of these antigens between these three groups." (PMID 33419040, 2021). "Furthermore, COVID-19 patients with severe respiratory failure show MAS or immune dysregulation, characterised by hyperactivated monocytes, CD4+ lymphopenia, B lymphopenia, and natural killer (NK) cytopenia." (PMID 34360684, 2021). "Regarding regulatory T (Treg) cell populations, significantly lower levels were observed in the case of critical COVID-19 (p = 0.001), both in terms of naïve (CD45RA+CD3+CD4+CD25+CD127low+) and induced (CD45RO+CD3+CD4+CD25+CD127low+) subsets (p < 0.001 and p = 0.007, respectively)." (PMID 34071149, 2021). "Only one study reported a CD4:CD8 ratio <1.2, in either severe or non-severe COVID-19, the CD4:CD8 ratio therefore remained within normal range in both non-severe and severe COVID-19." (PMID 35965490, 2021). "In accordance with the conclusion of previous studies, the neutrophils were significantly elevated, and the absolute counts of CD3+ T cells, CD3+CD4+ T cells, CD3+CD8+ T cells, CD19+ B cells, and NK cells were significantly decreased in patients with severe COVID-19." (PMID 34712741, 2021). "Strong signals among CD4+T cells, memory B cells, and monocytes in stage A indicate activation of BTLA in T and B cells in the early phase, which was in concordance with a previous report that severe COVID-19 expressed higher BTLA." (PMID 35095832, 2021). "In contrast, no identical CDR3 sequences were found in all CD4+ T cells of different convalescent COVID-19 patients." (PMID 35011632, 2021). "We found an expansion in the CD38+HLA-DR+ subset in all the non-naïve CD4 T cell subsets from COVID-19 patients, more significantly in the severe group." (PMID 33777054, 2021). "Studies have found that the CD4+ and CD8+ T cell counts are closely related to disease severity and clinical outcome, and therefore some authors proposed that CD4+ and CD8+ T cell counts in COVID-19 patients could be good biomarkers of COVID-19 activity." (PMID 33350432, 2021). "However, in COVID-19, there is a decrease in CD4+ and CD8+ T cell numbers and a delayed and limited production of γ-IFN by CD4+ T cells." (PMID 34573071, 2021).